FOXA1 (forkhead box A1)
Diseases named in the same sentence as FOXA1 in open-access papers (continued):
Sharing a sentence is not in itself a finding about the gene and the disease.
tumor (continued). "Supporting a role for SMARCD3 and FOXA1 in cancer stem cells, SMARCD3/FOXA1 interactions were enriched within the nuclei of primary CD133+ mouse tumor cells and Foxa1 knockdown severely reduced sphere formation in KPf/fC cells." (PMID 36653361, 2023). "To begin, we aligned the DEGs, and this allowed us to match the gene expression pattern in the FOXA1 mutant group with the list of oncogenes/driver genes and tumor suppressor genes in the CancerMine database." (PMID 37958805, 2023). "At the same time, compared with LUAD normal tissues, overexpression of FOXA1 in LUAD tumor tissues on the TCGA database." (PMID 37277890, 2023). "Invasion, proliferation and apoptosis capacity and tumor formation were decreased in the FOXA1-knockdown cells." (PMID 34991620, 2022). "Overrepresentation of targets for ESR1 and FOXA1 in the luminal subtypes is in line with the cooperation between these two transcription factors and the importance of oestrogen signalling in these tumours." (PMID 35182081, 2022). "Increasing studies substantiated that the FOXA1 overexpression can promote tumor metastasis, invasion, and proliferation, particularly in several hormone-independent cancers." (PMID 35273656, 2022). "As expected, combining nintedanib with either linsitinib or rapamycin significantly reduced Ki-67+ cells in FOXA1-expressing tumor sections." (PMID 35974000, 2022). "Meanwhile, FOXA1 also has a tumor-suppressive function by suppressing the PI3K signaling pathway, a potential cancer therapeutic target." (PMID 35273656, 2022). "For the expression of FOXA1 in single cell in OV, we found that FOXA1 was mainly expressed in malignant tumor cells, indicating that FOXA1 mainly plays its function in tumor cells." (PMID 36393971, 2022). "The results indicated that FOXA1 overexpression promoted tumor growth in terms of tumor weight and volume." (PMID 35968505, 2022). "We also predicted that FOXA1 was involved in the formation of tumor immunosuppressive microenvironment." (PMID 36393971, 2022). "In paired tumor and adjacent normal tissues, FOXA1 was overexpressed in BLCA, BRCA, CESC, LUAD, PAAD, PRAD, and STAD while low expressed in COAD, HNSC, KICH, KIRC, and READ." (PMID 36393971, 2022). "In this context, FOXA1 has been shown to alter the ER-cistrome leading to the expression of genes which potentiate more aggressive behaviour such as IL-8, which promotes tumour cell survival and metastasis." (PMID 36446866, 2022). "In pan-cancer research, we found that FOXA1 was highly expressed in most tumor types, including EOC." (PMID 36393971, 2022). "Forced expression of FOXA1 in A549 cells exerted minimal effect on xenograft tumor growth in nude mice." (PMID 35974000, 2022). "FOXP1 is likely a tumor-suppressor gene in primary PCa, whereas the function of FOXA1 is context-specific." (PMID 36139541, 2022). "LSD1 acts as a transcriptional repressor by associating with FOXA1 through the demethylation of H3K4; it also acts as an AR coactivator, and an LSD1 inhibitor suppresses tumor growth synergy with enzalutamide in CRPC cells." (PMID 36237332, 2022). "For the expression of FOXA1 in single cell in OV, we found that FOXA1 was mainly expressed in malignant tumor cells." (PMID 36393971, 2022). "Overall, we show by CRISPR alteration that Foxp1 is a tumor suppressor by interfering with the AR pathway and Foxa1 is required for luminal cells’ identity." (PMID 36139541, 2022). "FOXA1 functions as a cofactor for AR and can promote tumor growth independently even in some AR deletion cases." (PMID 35860692, 2022). "Subsequently, in in vivo experiments, we selected HeLa/DDP cells with stable low expression of FOXA1 for tumor xenograft experiments." (PMID 35498155, 2022).
tumor (continued). "FOXA1 co-regulates an AR-mediated transcriptional program in healthy prostate and in primary tumours via making response elements (ARE) accessible to AR and/or by direct interaction with AR itself." (PMID 34940756, 2021). "We observe that patients with PRAD tumours have higher expression of FOXA1 and HOXB13 compared to the normal prostate tissue and poor survival is associated with high FOXA1 expression." (PMID 34911933, 2021). "Using 3D cultures as an in vitro surrogate for tumor formation, we show that FOXA1 promotes anchorage independence, a key property of tumor initiating cells." (PMID 33417085, 2021). "Drug resistant cells normally acquire tumor formation capabilities and thus we tested how the experimental modulation of FOXA1 levels affected anchorage independence." (PMID 33417085, 2021). "Both types of translocation events hijacked the cis-regulatory activity of FOXA1 CREs to significantly upregulate the oncogenic expression of these genes, including FOXA1 in mCRPC tumours." (PMID 32946061, 2021). "In vitro, overexpression of FOXA1 in primary PDA tumor cells activated foregut developmental genes that promoted anchorage-independent cell growth and invasion in sphere-formation and Matrigel invasion assays, respectively." (PMID 34439749, 2021). "In line with this, isolated circulating tumor cells (CTC) from patients with abiraterone- or Enz-resistant metastasis showed gene amplification of FOXA1 in more than 30% of CRPC patients, pinpointing the critical role of FOXA1 in emerging DRPC." (PMID 33810413, 2021). "We also assessed the correlations between the expression of SLC39A6 and other well-characterised ER-related markers that have been identified as signature genes in ER + tumours, including FOXA1 and GATA3." (PMID 34453638, 2021). "We observe an enrichment for Fra1, Fra2, JunB, Atf3 and AP-1 in tumours with Gleason pattern 3 whereas tumours with Gleason pattern 4 show an enrichment for FOXA1, HOXB13 and CDX2." (PMID 34911933, 2021). "The tumor-specific SE-associated genes were enriched in important pathways, such as chordate embryonic development (RUNX2, FOXA1), regulation of cell adhesion (RUNX1, SOX2 and VEGFA), and epithelial cell differentiation (SOX9, ELF3)." (PMID 34001209, 2021). "Another feature associated with cancer progression, acquisition of anchorage independence, is elevated upon experimental FOXA1 overexpression, supporting its role in cancer progression by targeting genes that lead to tumor formation and drug resistance." (PMID 33417085, 2021). "In the current study, miR-4721 as a tumor promoter had a crucial role in the FOXA1 regulatory network and thus provided an insight into the FOXA1-mediated regulation of Nanog." (PMID 34503528, 2021). "In the context of pancreatic cancer, we identified that the developmental Forkhead family TF FOXA1 drives enhancer landscape reprogramming during PDA tumor-to-metastasis transition." (PMID 34439749, 2021). "Consistent with the importance of FOXA1 cis-regulatory landscape in disease progression, SVs were found to target loci harbouring the CREs in up to 30% of mCRPC tumours." (PMID 32946061, 2021). "PCa is generally a slow proliferating tumor with few key mutations and genetic alterations commonly found in patients such as TMPRSS-ERG, SPOP, FOXA1, PTEN35,36." (PMID 33602919, 2021). "Intrahepatic CCA patients who had low FoxA1 expression level in the tumor tissues showed significantly shorter survival rate." (PMID 32151057, 2020). "Altogether, these data indicate that FOXA1 can promote tumor progression or suppress tumor development depending on tumor type, which requires further studies to elucidate the function of FOXA1in tumor progression." (PMID 32685483, 2020). "KrasG12D activation with concomitant Nkx2-1 deletion (KrasLSL-G12D/+; Nkx2-1F/F) together with either Foxa1 or Foxa2 disruption was reported to promote squamous differentiation of tumor lesions." (PMID 32747478, 2020).
tumor (continued). "The expression of FoxA1 was reduced in intrahepatic CCA cells compared to NBD cells located at the tumor adjacent areas." (PMID 32151057, 2020). "(F) Decreased FOXA1 expression in CRC tumor samples compared to normal samples in the UMMC cohort is shown." (PMID 33112233, 2020). "We provide experimental evidence that restoration of either miR-100-5p or miR-125b-5p impaired the tumor suppressive activity of FOXA1 in HK1 cells." (PMID 32201519, 2020). "The Human Protein Atlas also reports appreciably higher FOXA1 protein expression in BC tumor samples as compared to TC by IHC analysis." (PMID 33102692, 2020). "Taken together, in CCA, FoxA1 is down-regulated and has tumor suppressive roles, whereas FoxA3 is up-regulated and has oncogenic roles." (PMID 32151057, 2020). "FOXA1 is significantly overexpressed in TNM stages (I-III) suggesting that FOXA1 decreases tumor progression in NPC." (PMID 32685483, 2020). "miR-132 is known as a tumor suppressor miR and some authors have associated it with reduced proliferation through its action on different targets (LAPTM4B, FOXA1)." (PMID 33505957, 2020). "They showed that FOXA1 acts as a tumor suppressor in NPC development through the control of the TGF-β stimulated transcription program." (PMID 32685483, 2020). "In different tumor tissues, FOXA1 can play a role in promoting or inhibiting the development of tumors." (PMID 32411194, 2020). "The favorable prognostic value of FOXA1 index ≥1% was also observed in cancer-specific survival independently of the pathologic tumor size, pathologic nodal stage and distant metastasis." (PMID 31888566, 2019). "Our previous study shows that FOXA1 mediates the tumor suppressive role of miR-212 in HCC tumor growth." (PMID 30782188, 2019). "For example, lncRNA- MCM3AP-AS1 promotes tumor growth by specific binding to miR-194-5p, thus sequestering the miRNA and inducing FOXA1 expression." (PMID 31752906, 2019). "In HCC, MCM3AP-AS1 is up-regulated and regulates miR-194-5p/forkhead box protein A1 (FOXA1) axis to promote tumor growth." (PMID 31836002, 2019). "Both AR and FOXA1 were strong and favorable prognostic factors, independently of tumor stage at diagnosis." (PMID 31888566, 2019). "The expression of FOXA1 protein in tumor tissues from MCM3AP-AS1 knockdown injected mice was significantly lower than that in control mice (P < 0.05)." (PMID 30782188, 2019). "FOXA1 was present in 91.1% (113/124) of tumor samples and it was overexpressed in 32.7% (37/113) of them." (PMID 31540486, 2019). "By contrast, 95% and 76% of evaluable cases stained for GATA3 and FOXA1 in >80% of tumor cells, respectively." (PMID 30699951, 2019). "The expression of NR2F1-AS1, miR-483-3p, and FOXA1 protein in the tumor xenografts was measured next." (PMID 31801112, 2019). "For all three tumor types, a substantial increase in data quality was observed for ERα, AR, and FOXA1 with strong increased peak intensity, as compared to single fixation procedure using FA." (PMID 30620009, 2019). "As a whole, these results confirmed the role of miR-483-3p as a tumor-suppressive miRNA in OS and identified FOXA1 as a direct target gene of miR-483-3p in OS." (PMID 31801112, 2019). "Accordingly, a down-regulation of the luminal-specific transcription factor Foxa1 was induced after BPA treatment in triple negative tumor cell lines leading to EMT induction and increased cell motility." (PMID 31547326, 2019). "Tumour size, nodal involvement and AR/FOXA1 co-expression were found independent poor prognostic factors in multivariate analysis, while lobular histology, adjuvant chemotherapy and TILs density were associated with a longer OS." (PMID 29880907, 2018). "AR + /FOXA1- and AR- tumours more frequently exhibited a staining of > 50% of TILs, compared to AR + /FOXA1 + tumours (10–50% of stained TILs more frequent)." (PMID 29880907, 2018). "42.4% patients had AR + /FOXA1 + tumours, 48 (15.8%) had AR + /FOXA1- tumours and 127 (41.8%) had AR- tumours." (PMID 29880907, 2018).
tumor (continued). "Our results support the evidence of those studies, showing that BC tumor with high mRNA level of FOXA1 are generally ER and AR enriched." (PMID 29970021, 2018). "We found that concomitant deletion of both Foxa1 and Foxa2 led to an approximately 10-fold reduction in tumor burden when measured at 5 weeks post-initiation." (PMID 30475207, 2018). "RFS was significantly shorter for AR + /FOXA1 + tumours compared with other tumours (AR + /FOXA1- and AR-) (p = 0.020)." (PMID 29880907, 2018). "This is consistent with our data, where we find FOXA1 generally increased relative to the primary tumor in metastases to the skin and brain." (PMID 29972720, 2018). "FOXA1 and FOXA2 are also associated with a variety of cancers, and their behaviors are tumor type-specific, with a dependence on the particular transcriptome interactions." (PMID 30360388, 2018). "AR + /FOXA1 + tumours (42.4%) were more frequently: found in older patients, lobular, of lower nuclear grade, with more frequently PIK3CA mutations; exhibited less frequently BRCA1 promoter methylation, defects of PTEN and PD-L1 expression than others." (PMID 29880907, 2018). "Prior cell line‐based reports, however, have revealed that FOXA1 is required for tamoxifen‐resistant tumor cell proliferation." (PMID 29972720, 2018). "Patients with immunohistochemically AR(-)/FOXA1(-) tumor frequently showed node metastasis, high grade, and high Ki-67 proliferation, therefore, significantly worse survival in ER-positive disease." (PMID 29137314, 2017). "Upon exposure to hepatocarcinogens, the tumor load in mutant FOXA1/A2 female mice was dramatically increased whereas the tumor load in mutant FOXA1/A2 male mice was dramatically decreased." (PMID 28673244, 2017). "Further molecular mechanistic studies have revealed that FOXA1 promotes tumor progression by recruiting other transcription factors, while acting as a transcription factor for suppressing tumor development by directly regulating target gene expression." (PMID 29208003, 2017). "As a tumor suppressor, FOXA1 targets PIK3R1 directly to inhibit PI3K/Akt signaling pathway, thus exerting a negative regulatory effect on proliferation, migration, and invasion of HCC in male patients." (PMID 29208003, 2017). "For example, it has been reported that miR-212 suppresses tumor growth of HCC by targeting forkhead box protein A1 (FOXA1)." (PMID 29029464, 2017). "NANOG has previously been shown to be involved in tumor progression and castration resistance by binding to the androgen receptor/FoxA1 signaling complex." (PMID 29156833, 2017). "Next, we focused on the identification of genes under the control of FoxA1 and FoxA2 with the capacity to support tumour growth in xenograft tumours from implanted MCF7 and MDA231 cells, with a specific focus on metabolic functions." (PMID 27045898, 2016). "Recent data have shown that tumours that enrichcells with GATA3 mutations tend to be ductal cancers, whereastumours that possess FOXA1 mutations tend to be of the lobularsubtype." (PMID 26884552, 2016). "In our motif searches, the validated AR-cooperating transcription factor FOXA1 displayed motif enrichment, differential up-regulation, and high tumor expression, serving as test and validation data point." (PMID 27623747, 2016). "Immunohistochemistry of ER andFOXA1 in metastatic tumour material showed that FOXA1 is expressed in almost allsolid distant metastases, and that correlation between ER and FOXA1 proteinexpression is high." (PMID 26884552, 2016). "The data further underpin distinct functions of Foxa1 and Foxa2 in both embryonic and tumor development." (PMID 26395490, 2015). "Multivariate Cox regression analysis showed that miR-212 level, FOXA1 expression, tumor size, TNM stage and Edmondenson stage were independent prognostic predictors for both OS and DFS." (PMID 25965836, 2015). "Nuclear localization of Foxa1 typically distinguished the peripheral zone from central portions of tumor nodules." (PMID 26395490, 2015).
tumor (continued). "Tumor cell proliferation was correlated with nuclear accumulation of Foxa1, and a direct role of Foxa1 in MTC growth regulation was also indicated in knockdown experiments in vitro." (PMID 26395490, 2015). "Meanwhile, increased expression of FOXA1 was correlated with large tumor size (P < 0.001), venous infiltration (P = 0.002), high Edmondson-Steiner grading (P = 0.028), and advanced TNM stage (P < 0.001)." (PMID 25965836, 2015). "This showed generally strong immunoreactivity for Foxa1 and Foxa2 in both primary tumor nodules and lymph node metastases." (PMID 26395490, 2015). "The critical role of miR-212 and FOXA1 in the tumor growth and their aberrant expressions in HCC tissues promoted us to examine their clinical significance." (PMID 25965836, 2015). "Measurements of protein expression by immunohistochemistry on an independent set of early neoplasias confirms that ER pathway regulators FOXA1 and GATA3, as well as ER itself, are consistently upregulated at this early stage." (PMID 24887547, 2014). "This confirms that FOXA1 and GATA3 expression is commonly and recurrently elevated in the majority of early neoplasias (40/59 cases strong and 15/59 cases intermediate staining for FOXA1; 31/57 cases strong and 21/57 cases intermediate staining for GATA3)." (PMID 24887547, 2014). "Here we observed that this transcript is significantly elevated in early neoplasias compared to normal tissue using both 3SEQ and RNA in situ hybridization, and it shows correlated expression with the ER pathway members ER, FOXA1, and GATA3." (PMID 24887547, 2014). "In summary, our results suggest a new mechanism for the development of EC, in which FOXA1 promotes tumor cell proliferation through AR and activates the Notch pathway by influencing AR expression." (PMID 24512546, 2014). "In the present study, we investigated the dependency of AR on FOXA1 expression in tissue paraffin sections, in multiple cellular contexts, and on tumor-bearing nude mice." (PMID 24512546, 2014). "Tumors generated by subcutaneous implantation of MFE-296 cells were used to evaluate the effect of FOXA1 on proliferation in a mouse tumor xenograft model." (PMID 24512546, 2014). "Tumor tissues were then embedded in paraffin, stained with hematoxylin and eosin (H&E), and immunohistochemically stained with antibodies against FOXA1, AR, Notch1, Hes1, Ki67, or PCNA." (PMID 24512546, 2014). "Over the past decade, FOXA1 expression has been examined in several human cancers, and oncogenic and tumor-suppressive roles have been proposed for FOXA1 depending on the cancer type and, in some cases, the subtype." (PMID 24512546, 2014). "Focal amplification of 14q21.1 was found in three independent lesions isolated from a single patient, suggesting amplification of the FOXA1 genomic region is an early event in progression of this tumor." (PMID 23420418, 2013). "In the present study we demonstrate that MMTV-NeuNT tumors have reduced expression of Foxa1 relative to non-tumor bearing mammary glands." (PMID 23593223, 2013). "Instead, our data demonstrates that KDM4B is a key regulator of ER gene transcription and FOXA1 expression that together control the estrogen-dependent phenotype of a high proportion of BCa cell lines and primary tumours." (PMID 23723241, 2013). "In agreement with in vitro findings, FOXA1 knockdown resulted in significantly increased in vivo tumor volume." (PMID 22590586, 2012). "It is important to note that logistic regression analysis of all histologic tumor types and the separate subset of UCC tumors alone revealed a significant association between loss of FOXA1 and increasing tumor stage." (PMID 22590586, 2012). "A high level of FOXA1 was previously found in 89% of metastatic PC and the expression of FOXA1 was positively correlated with tumor size, extraprostatic invasion, AR and lymph node invasion." (PMID 22879989, 2012).